CD36 (CD36 molecule (CD36 blood group))
Diseases named in the same sentence as CD36 in open-access papers (continued):
Sharing a sentence is not in itself a finding about the gene and the disease.
Obesity (continued). "The results of both studies demonstrate that obesity can modulate the effect of CD36 on fat taste sensitivity and preference." (PMID 36409650, 2023). "CD36 is important for fatty acid uptake and release in adipocytes and its expression is increased in adipose tissue in human obesity." (PMID 37242220, 2023). "We found that CD36 peptide treatment didn’t affect obesity or weight gain but significantly reduced proinflammatory cytokine production systemically and in visceral fat tissue." (PMID 37980376, 2023). "Control or CD36 peptide treatment was conducted in male C57BL6 mice after 14 weeks of high fat diet feeding when these mice developed obesity, chronic inflammation, and insulin resistance as compared to low fat feeding (LF) groups." (PMID 37980376, 2023). "dKO mice were phenotypically similar to both Cd36-deficient and Dlk1 transgenic mice, namely in decreased amounts of WAT and resistance to HFD-induced obesity." (PMID 37603466, 2023). "In this context, both strength and endurance training have been shown to reduce the obesity-related increase in CD36." (PMID 37510432, 2023). "To further test the effect of obesity and its complications on CD36 expression in the skeletal muscle cells, we established a suitable culture condition by differentiating C2C12 cells with a PA-containing medium, which mimics HFD conditions in vitro." (PMID 36979708, 2023). "Consistently, in this study, CD36 petide mediated TSP1 antagonization attenuated obesity-induced kidney damage." (PMID 37980376, 2023). "This study found that, compared to the normal weight group, the obesity group expressed higher TLR4, CD36, and NF-κB p65 in monocytes; the obesity group expressed higher TLR4 and CD36 in lymphocytes; and the obesity group expressed higher CD36 in granulocytes." (PMID 37403139, 2023). "CD36 was also enriched in the “role of adipose tissue hypoxia in obesity and type 2 diabetes” pathway, and it is a shared target of LXR, PXR, and PPAR-gamma." (PMID 36816031, 2023). "Compared to the control group, in monocytes the obesity group expressed higher TLR4, CD36, and NF-κB p65 in lymphocytes, the obesity group expressed higher TLR4 and CD36; and in granulocytes the obesity group expressed higher CD36." (PMID 37403139, 2023). "The CD206hi ESAM+ KC2 regulate liver metabolism in the obese murine model of obesity by expressing the fatty acid transporter CD36." (PMID 37377968, 2023). "This obesity-induced liver damage was attenuated by the CD36 peptide treatment showing reduced plasma ALT levels and liver fat accumulation." (PMID 37980376, 2023). "CD36 is believed to be involved in the development of adipose tissue insulin resistance in humans and is increased in adipocytes during obesity." (PMID 37242220, 2023). "Adipose tissue in the setting of obesity is another microenvironment where metabolic regulation by CD36 plays an important role." (PMID 35438721, 2022). "For example, obesity altered the expression of CD36, which was correlated with FA transport and has been associated with cancer progression." (PMID 36209108, 2022). "Detailed investigations by several independent research groups have revealed that CD36 plays a key early role in the development of obesity-induced insulin resistance and type 2 diabetes." (PMID 35125400, 2022). "For example, CD36 is normally highly expressed in AT and is up-regulated further in obesity and T2DM." (PMID 35348641, 2022). "Consistent with increased circulating lipids and fatty acids in obesity, a 6-month WD induced increased expression of fatty acid and lipid transporters Cd36, Fabp4, Fabp5 and Abca1 in liver ECs, which was partially restored by the reversion diet." (PMID 36400935, 2022). "CD36 is a class B scavenger receptor that is involved in the pathogenesis of metabolic dysregulation in obesity, insulin resistance, and atherosclerosis." (PMID 36465448, 2022).
Obesity (continued). "Studies have previously reported an increased expression of CD36 in adipose tissue during obesity and in individuals with high intrahepatic triacylglycerol levels." (PMID 36467688, 2022). "Most CD36 DNA methylation data derive from genome-wide studies focused on metabolic diseases such as obesity, and only one study focused on cancer reported the correlation of CD36 DNA hypermethylation with progression in lung tumours." (PMID 35215499, 2022). "CD36 accelerates the transport of long-chain fatty acids and is overexpressed in diet-induced obesity." (PMID 35625757, 2022). "During consumption of a Western (high fat-containing) diet and in obesity the heart is subject to a chronic oversupply of fatty acids, which triggers the enhanced recruitment of CD36 to the sarcolemma." (PMID 35125400, 2022). "Cluster of differentiation 36 (CD36) was significantly upregulated in myotubes from donors with obesity." (PMID 36467688, 2022). "We found a 3-fold increased expression of CD36 in myotubes from donors with obesity in the present study." (PMID 36467688, 2022). "Animal studies support a role for CD36 in impaired glucose tolerance and insulin signalling in obesity as well as macrophage infiltration into AT and overproduction of inflammatory cytokines and chemokines." (PMID 35348641, 2022). "Increased CD36 expression in both macrophages and adipocytes of the adipose tissue induces inflammation in obesity." (PMID 36557031, 2022). "It was previously observed that CD36 deficiency reduces NOX activity and attenuates obesity-associated oxidative stress in the heart." (PMID 34360006, 2021). "Studies have shown that oocytes from aged mice and obesity females show higher expression of CD36, suggesting the elevated lipid uptake." (PMID 34481496, 2021). "Our results also showed that CD36 was more highly expressed in T2DM with normal weight than T2DM with obesity." (PMID 34085602, 2021). "It has also been reported that CD36-dependent inflammation and the apoptosis of adipocytes in response to diet-induced obesity reduces insulin sensitivity." (PMID 34360006, 2021). "-With respect to B cells: Does CD36 coordinate lysosomal function in B cells and is it altered during obesity?" (PMID 34957117, 2021). "In duodenal mucosa biopsies from human, the CD36 expression is also positively correlated with increasing body mass index (BMI), suggesting the dysregulation of CD36 responses to fat in obesity." (PMID 33995128, 2021). "HDAC3 also synergistically activates estrogen-related receptor α (ERRα), induces microbiota-dependent rhythmic transcription of the lipid transporter gene CD36, and promotes lipid absorption and diet-induced obesity." (PMID 34203243, 2021). "We examined if diet-induced obesity affects LEC CD36 expression in WT mice fed a high-fat diet (HFD) for 12 weeks." (PMID 34099721, 2021). "CD36, the main trans-membrane translocase of FAs, was decreased in gene level in obesity, and increased after LCA treatment." (PMID 34899326, 2021). "CD36 is present in humans and mice with NAFLS, also contributing to dyslipidemia that is associated with HD-induced obesity in C57BL6 mice." (PMID 32079362, 2020). "Salvianolic acid B, a CD36 antagonist, counteracts obesity-induced macrophage infiltration and inflammation in adipose and hepatic tissues." (PMID 32796572, 2020). "Obesity‐induced upregulation of NR2F6 promotes the expression of CD36 in the liver, thereby facilitating fatty acid uptake and triglyceride retention, contributing to NAFLD and insulin resistance." (PMID 33173745, 2020). "We then sought to explore the physiological function of CD36-mediated endocytosis of FAs on diet-induced obesity in mice." (PMID 32958780, 2020).
Obesity (continued). "The key event initiating the infiltration of macrophages to WAT is the CD36-dependent inflammatory response and apoptosis of adipocytes in response to diet-induced obesity." (PMID 32796572, 2020). "Our results showed that NR2F6 has a steatotic role in the development of obesity‐associated NAFLD and insulin resistance through direct upregulation of CD36 expression." (PMID 33173745, 2020). "Pioglitazone has shown mixed effects on CD36 levels in patients and animal models of diabetes and obesity." (PMID 31910209, 2020). "Glucagon-like peptide 1 (GLP1), the hormone of intestinal L-cells with potential cardioprotective action in DM and obesity, preventing palmitate-induced CD36 translocation and lipid accumulation by the activation of GLP1R/Akt-dependent pathway." (PMID 32796572, 2020). "CD36 is currently investigated as a potential therapeutic target in cardiovascular disease, metabolic syndrome, and obesity." (PMID 31379931, 2019). "Chronic inflammation, a feature of obesity, is known to induce CD36 expression, which can aggravate kidney damage and accelerate the disease progression." (PMID 30925738, 2019). "On the other hand, in a rat model of diet-induced obesity that is associated with IUGR, mRNA and protein levels of CD36, Slc27a1/Fatp1 and Slc27a4/Fatp4 were reported as decreased relative to control." (PMID 31774824, 2019). "Currently, most of the data regarding changes in CD36 DNA methylation come from genome-wide or epigenome-wide studies focusing on obesity and metabolic disorders, such as diabetes." (PMID 31379931, 2019). "Here, we demonstrated that mice harboring an overexpression of miR-29a presented suppressed CD36 abundance, as well as reduced body weight and adipose tissue of various parts, in line with the notion of targeting CD36 to mitigate obesity." (PMID 31652636, 2019). "As an integral membrane protein present on the surface of various cell types in vertebrate 4, CD36 antigen was involved in adipose metabolism and individual obesity 4-7." (PMID 31528216, 2019). "Those with similar patterns of cancer driver gene expression have poorer prognoses when they express higher levels of a subset of genes related to obesity or lipid metabolism (e.g. CD36 or TGF‐ß)." (PMID 29266765, 2018). "Our group also noticed that cardiac FAT/CD36 mRNA levels increase during HFD-induced obesity in both WT and IL-6−/− mice." (PMID 30134607, 2018). "In the past decade, microvesicles (MVs) and CD36 have increasingly been considered as possible biomarkers for obesity, the metabolic syndrome (MetSy), type 2 diabetes mellitus (T2DM)." (PMID 30386406, 2018). "The up-regulated expression of CD36 was observed in some pathological conditions such as obesity, diabetes and non-alcoholic fatty liver disease, resulted in the increasing uptake of free fatty acids into the liver." (PMID 29593573, 2018). "The expression of CD36 is upregulated by insulin, and the expression in adipose tissue is also upregulated in obesity and in type 2 diabetes patients." (PMID 29075849, 2018). "CD36 is a pattern recognition receptor that exhibits increased expression in obesity as well as in AD, where it mediates recruitment of microglia to Aβ deposits." (PMID 30396359, 2018). "Recent findings suggested that increased hepatic CD36 activity is critical for the development of steatosis under pathologic conditions such as HF diet, obesity, and diabetes." (PMID 30363699, 2018). "Taken together, increased numbers of CD36+ MMVs can therefore be proposed as possible blood-based biomarkers for ectopic fat accumulation in obesity, MetSy, and T2D." (PMID 28168203, 2017). "Our study reveals that absence of TIMP4 can impair lipid absorption and the high fat diet-induced obesity in mice possibly by regulating the proteolytic processing of CD36 protein in the intestinal enterocytes." (PMID 28740132, 2017).
Obesity (continued). "We show that lysophosphatidic acid/protein kinase D1 (LPA/PKD-1)-CD36 signaling is a bona fide breast cancer promoter via stimulating microvascular remodeling in chronic diet-induced obesity (DIO)." (PMID 28186980, 2017). "Elevated expression of CD36 was also observed in mouse models with genetic obesity and high-fat-feeding-induced fatty livers." (PMID 28770225, 2017). "With this in mind, we aimed to explore the role of CD36 in obesity-induced cardiac steatosis and lipotoxicity in the Lepob/ob mice model." (PMID 27195707, 2016). "Several polymorphisms on CD36, CPT, ACS and FABP had been shown to be related to obesity either by regulating enzymatic activity or directly influence fatty acid oxidation process." (PMID 27127449, 2016). "A study done in European adolescent population showed that four SNPs in CD36 (rs3211867, rs3211883, rs3211908 and rs1527483) was related to obesity, BMI and percentage of body fat." (PMID 27127449, 2016). "Growing number of evidences have suggested that oral fat sensing, mediated by a glycoprotein CD36 (cluster of differentiation 36), plays a significant role in the development of obesity." (PMID 26556365, 2015). "Cardiospecific CD36 inhibition protects against the aggravation of cardiac functional and morphological changes associated with HFD induced obesity." (PMID 26036798, 2015). "Cd36 mRNA levels are drastically increased in livers of murine models of obesity and T2D, and CD36 expression correlates with liver TG accumulation, insulin resistance, and hyperinsulinemia in human NAFLD." (PMID 26085100, 2015). "Other genes involved in obesity (e.g., Cidec, Cd36), diabetes (Igfbp1), inflammation (Cd63), mitochondrial function (Pdk4) and cancer (H19) were also upregulated by the soybean oil diet." (PMID 26200659, 2015). "Our results provide additional evidence for the importance of CD36 as a cardiac FA transporter and the indispensable of CD36 in the development of obesity-related myocardial lipid accumulation." (PMID 26036798, 2015). "The adverse effect of HFD-induced obesity on cardiac function was prevented by inhibition of the FA transporter CD36." (PMID 26036798, 2015). "For example, Ntrk2 shows a similar induction pattern as CD36 and has also been shown to play a role in breast cancer cell survival and obesity." (PMID 25984797, 2015). "Taken together with the cardiac hypertrophic growth data, these results indicate that the inhibition of cardiac CD36 protects against obesity-related cardiac hypertrophy and systolic dysfunction." (PMID 26036798, 2015). "A soluble form of CD36 (sCD36), a marker of altered tissue CD36 expression, was recently identified in human plasma, and elevated levels were found in obesity and type 2 diabetes." (PMID 24766787, 2014). "Increased CD36 expression in human and rodent models is commonly related to insulin resistance and type 2 diabetes, including high-fat (HF) feeding and obesity and is also observed in the physiological aging process." (PMID 24751397, 2014). "The target genes regulated by PPARα and involved in lipid metabolism and obesity include CD36, LPL, ACC, ABCA1, CYP4a10, CYP4a14, UCP2, ACO and SCD1." (PMID 24705395, 2014). "An abnormal cell surface CD36 location was also found in muscular cells derived from obese patients, suggesting that obesity affects the distribution of CD36 in different cell types." (PMID 23840049, 2013). "Activation of Cd36 facilitates free fatty acid uptake from circulation and also contributes to obesity, hepatic steatosis and type-2 diabetes." (PMID 22723881, 2012). "Our study confirms that CD36 contributes to high fat diet-induced obesity and insulin resistance and shows that CD36 enhances adipocyte cell death and WAT inflammation through its expression in both adipocytes and macrophages." (PMID 22615812, 2012). "CD36 KO mice were found to be leaner than control (WT) mice following 16 weeks of a high-fat ‘obesity’ diet containing 60% (kcal) fat." (PMID 22615812, 2012).
Obesity (continued). "Reduced immune cell infiltration in CD36 KO WAT was accompanied by a reduced inflammatory response to diet-induced obesity compared to WT mice." (PMID 22615812, 2012). "Except for inhibiting lipogenesis, a more important characteristic of PXR in diet-induced obesity was reduction of lipid uptake in liver and adipose, confirmed by inhibiting up-regulation of Cd36 expression by high-fat diet." (PMID 22723881, 2012). "The objective of this study was to investigate the role of the scavenger receptor CD36 in high fat diet-induced obesity and adipose tissue inflammation and cell death." (PMID 22615812, 2012). "The reduced cell death and inflammatory responses, as well as reduced obesity in CD36 KO mice were accompanied by improved insulin sensitivity, as recently reported by others." (PMID 22615812, 2012). "CD36 enhances adipose tissue inflammation and cell death in diet-induced obesity through its expression in both macrophages and adipocytes." (PMID 22615812, 2012). "Given that adipocyte cell death is a contributor to inflammation and dietary obesity, elucidation of the molecular mechanisms responsible for CD36-dependent adipocyte cell death is key to understand how CD36 influences diet induced obesity." (PMID 22615812, 2012). "Our findings indicate that CD36 promotes adipocyte and macrophage cell death in adipose tissue during diet-induced obesity." (PMID 22615812, 2012). "In summary, the current study provides new understanding of the role of CD36 in adipose tissue function and diet induced obesity." (PMID 22615812, 2012). "Our finding that CD36 expression in both cell types markedly impacted such a synergistic inflammatory response therefore provides new insight into the etiology of obesity in which interactions between adipocytes and macrophages are important determinants." (PMID 22615812, 2012). "In this study, we investigated the role of CD36 in the development of obesity, focusing on its role in WAT inflammation." (PMID 22615812, 2012). "In keeping with these findings, the scavenger receptor CD36 was markedly increased in human obesity." (PMID 21298111, 2011). "Furthermore, KC2s have been implicated in the regulation of lipid processing in the liver via CD36 and targeted depletion of these cells prevented diet-induced obesity in mice, suggesting that KC2s promote MAFLD." (PMID 41451197, 2025). "However, when combined with HFD, the significant elevation of CD36 expression in mice resulted in the accumulation of lipids in the liver, despite the overall low energy intake of the body, preventing obesity." (PMID 40562101, 2025). "This study elucidates the critical role of CD36 in obesity-associated SAP and suggests that inhibiting CD36 function may provide a novel potential strategy for the prevention and treatment of this disease." (PMID 40331957, 2025). "Importantly, chronic CD36 membrane localization, often seen in obesity, enhances FFA influx, promoting intramyocellular lipid accumulation that impairs insulin-stimulated GLUT4 translocation and exacerbates local insulin resistance." (PMID 41002965, 2025). "In particular, STAT3 directly binds to the CD36 promoter to enhance its transcription, thereby promoting adipocyte differentiation and lipid accumulation, which in turn contributes to lipid metabolic dysregulation and obesity pathogenesis." (PMID 41345744, 2025). "The exact role of CD36 in liver steatosis may depend on other complications such as obesity, diabetes, chronic inflammation, insulin resistance and maybe cardiovascular disease." (PMID 40110132, 2025). "CD36 expression and its soluble form may be modulated by epistatic interactions, clinical conditions (hyperglycemia, obesity, hypertension), and environmental factors like sedentary lifestyle or smoking." (PMID 40867895, 2025). "The inhibition of CD36 could provide novel viewpoints for the prevention and treatment of obesity-related SAP." (PMID 40331957, 2025).